U3 (Small nucleolar RNA U3 )
Synonyms: LOC124905291
Gene: Small nucleolar RNA gene on chromosome X (113,944,186 to 113,944,399, reverse strand). Ensembl gene ENSG00000201674.
Gene Ontology:
Biological process: RNA processing
Cellular component: nucleolus
Homologues: Orthologues: chimpanzee U3 (99% identical), macaque U3 (99% identical). Paralogues in human: SNORD3P1 (80% identical), SNORD3G (79% identical), U3 (78% identical), SNORD3E (78% identical), U3 (77% identical), U3 (76% identical), U3 (75% identical), U3 (74% identical), U3 (73% identical), SNORD3D (73% identical), U3 (72% identical), U3 (71% identical), and 10 more.